YAP1 (Yes1 associated transcriptional regulator)
Diseases named in the same sentence as YAP1 in open-access papers (continued):
Sharing a sentence is not in itself a finding about the gene and the disease.
lung adenocarcinoma (continued). "We have also demonstrated that YAP1 induces STAT3 phosphorylation in lung adenocarcinoma cells by increasing expression of interleukin-6 (IL-6) (manuscript under review)." (PMID 31137841, 2019). "The Hippo pathway is a kinase cascade stimulated by the YAP1 oncogene, the activation of which is associated with resistance to EGFR inhibitors in EGFR-mutated lung adenocarcinoma." (PMID 30404194, 2018). "Using lung adenocarcinoma cell lines, enhanced YAP1 expression and activity mediated by EGFR signaling was detected through enhanced protein stability." (PMID 29163769, 2017). "This study provides evidence that YAP1 can act as a promising alternative therapeutic target in patients with EGFR-mutant lung adenocarcinoma, including those with EGFR T790M." (PMID 29163769, 2017). "Our data provide evidence that YAP1 can act as a promising therapeutic target for EGFR-depenedent lung adenocarcinoma." (PMID 29163769, 2017). "In this study, we have addressed the importance of YAP1 in lung adenocarcinomas by identifying YAP1 as an important EGFR downstream mediator regulating cell growth." (PMID 29163769, 2017). "Dasatinib, verteporfin and fluvasatin, all the three YAP1 inhibitors targeting via different mechanisms effectively reduced viability in EGFR-dependent lung adenocarcinoma cells." (PMID 29163769, 2017). "In the human lung adenocarcinoma tissue sample analysis, a correlation between EGFR mutation status and YAP1 expression was detected." (PMID 29163769, 2017). "This study investigated the roles of YAP1 in lung adenocarcinoma by exploring its regulation and functions mediated by EGFR signaling." (PMID 29163769, 2017). "The important roles of YAP1/YES in EGFR-mutant lung adenocarcinoma cells make it a potential therapeutic target for EGFR-dependent cells." (PMID 29163769, 2017). "The xenograft tumor results indicated that YAP1 was essential for tumor growth in EGFR-dependent lung adenocarcinomas in vivo." (PMID 29163769, 2017). "We suggest that through bypassing the driving oncogene EGFR itself, the YAP1 pathway can act as a promising alternative therapeutic target for lung adenocarcinoma patients with EGFR-dependency including those with EGFR T790M gatekeeper mutation." (PMID 29163769, 2017). "In this study, we detected a correlation between YAP1 level and EGFR mutation status in lung adenocarcinoma tissues." (PMID 29163769, 2017). "The nuclear YAP1 staining was positive in 50% of lung adenocarcinoma, 59% of squamous cell carcinoma and 32% of large cell carcinoma, respectively." (PMID 26716514, 2016). "A large-scale study of phosphoproteome in human lung cancer A549 cells allowed for the identification of a new phosphoprotein (YAP1), phosphorylated at Ser127, which seemed to be a promising lung adenocarcinoma biomarker." (PMID 28250368, 2014). "Yes-associated protein 1 (YAP1) is a nuclear effector of the Hippo pathway that plays an important role in tumorigenesis and progression in lung adenocarcinomas." (PMID 25337673, 2014). "The fact that its expression resulted in clearly decreased in cancer cells and tissues as compared to controls suggested YAP1 to be a promising lung adenocarcinoma biomarker." (PMID 28250368, 2014). "METTL3 mediated YAP1 m6A modification promotes liver metastasis of lung adenocarcinoma." (PMID 40097750, 2025). "The results suggest that LINC01117 may affect the migration and invasion of lung adenocarcinoma cells by influencing the expression of EMT transcription factors through the entry of YAP1 into the nucleus, providing a potential target for the treatment of LUAD." (PMID 37384755, 2023). "Furthermore, examination of a TCGA lung adenocarcinoma cohort validated that PD-L1 (CD274) was positively correlated with YAP (YAP1), TAZ (WWTR1), and the YAP/TAZ signature, and NSCLC patients with high PD-L1 expression conferred poor survival probabilities." (PMID 34073318, 2021).
lung adenocarcinoma (continued). "In this family, individuals in whom YAP1 mutation was detected (smokers and never-smokers, aged 50–89 years) had been diagnosed with lung adenocarcinoma or were being monitored due to the detection of ground-glass opacities." (PMID 32104210, 2020). "Because of the high toxicity profiles of compounds that target Yap1, the use of Abl allosteric inhibitors may be a promising new therapeutic strategy for lung adenocarcinoma patients." (PMID 30956771, 2019). "Our group recently demonstrated that YAP1 regulates the generation and expansion of CSCs in urothelial carcinoma of bladder and lung adenocarcinoma and that pharmacological inhibition of YAP1, in combination with chemotherapies, suppresses cancer progression by attenuating cancer stemness features." (PMID 31137841, 2019). "To determine whether DGUOK may regulate YAP1 expression in lung adenocarcinoma patients, we examine the correlation between DGUOK expression levels and YAP1 levels in the lung adenocarcinoma tissue microarray." (PMID 31633874, 2019). "We therefore were interested in whether YAP1 inhibitions through other mechanisms can also affect EGFR-dependent lung adenocarcinoma cells." (PMID 29163769, 2017). "Axl may be positively regulated by YES-associated protein 1 (YAP1); knockdown of YAP decreases both Axl and PCNA expression, and inhibits proliferation of lung adenocarcinoma cells." (PMID 25344858, 2014). "Compared to normal lung tissue, YAP1 was shown overexpressed in lung adenocarcinomas, and knockdown of YAP1 markedly downregulated the expression of AXL and inhibited the proliferation and invasion of lung adenocarcinomas suggesting that AXL is a mediator of the oncogenic function of YAP1." (PMID 25337673, 2014). "Importantly, YAP1 activation in lung adenocarcinoma has been shown to induce ZEB2 expression." (PMID 41002380, 2025). "The amplifications of MYC, YAP1, and MMP13, as well as the deletion of CDKN2A/B, contributed to LC-BrMs originating from lung adenocarcinoma." (PMID 39593114, 2024). "As in our previous studies in human UCB and lung adenocarcinoma (LUAD) cell lines, MB49 YAP1-KD clones formed smaller and fewer spheres compared with control cells." (PMID 39630608, 2024). "Through further GEPIA analysis of lung adenocarcinoma and lung squamous cell carcinoma data in the TCGA database, RUNX1 and YAP1 were found to be negatively-correlated." (PMID 33061847, 2020). "YAP1 confers chemoresistance in NSCLC cells, and YAP1 inhibition restores the sensitivity to EGFR-TKI in TKI-resistant lung adenocarcinoma." (PMID 29435131, 2018). "By reducing YAP1 activity through different mechamnisms, EGFR-dependent lung adenocarcinoma cells were effectively killed." (PMID 29163769, 2017). "YAP1 was a poor prognostic factor of EGFR-mutant NSCLC population rather than lung adenocarcinoma (LUAD) patients." (PMID 37388902, 2023). "This suggests that LINC01117 may regulate the activity of the Hippo pathway by altering the nuclear and cytoplasmic distribution of YAP1, which in turn induces the EMT process in lung adenocarcinoma cells and thus exerts a pro-cancer effect." (PMID 37384755, 2023). "The expression of SAV1 was significantly upregulated in BEAS2B cells overexpressing YAP1, however, there was no upregulation in the expression of YAP1 overexpressing lung adenocarcinoma cells HCC827 and lung squamous cell carcinoma cells H2170." (PMID 35864957, 2022). "In gastric and lung adenocarcinoma, tyrosine kinase AXL is the direct functional target of YAP1." (PMID 30961610, 2019). "Indeed, genetic inhibition of both YAP1 and STAT3 decreased the stem cell-like features of lung adenocarcinoma cells, resulting in reduced proliferation and enhanced cisplatin sensitivity." (PMID 31137841, 2019). "The YAP1 inhibiting properties of statins and its ability to kill EGFR-mutant lung adenocarcinoma cells may provide some evidence explaining this interesting phenomenon." (PMID 29163769, 2017).
lung adenocarcinoma (continued). "From the data presented here, it appears that the Hippo kinase-mediated phosphorylation of YAP1 may not be the only major mechanism regulating YAP1 levels in lung adenocarcinomas and that other modifications might regulate YAP1." (PMID 35937460, 2022).
glioblastoma (47 papers, 2015 to 2025). The most malignant astrocytic tumor (WHO grade IV). "In the context of glioblastoma, we have shown that YAP1 is essential for PTEN deficiency-induced transcriptional upregulation of LOX, which, in turn, triggers macrophage infiltration into the TME3." (PMID 38443336, 2024). "This represents a 2.3-fold enrichment over random control regions (hypergeometric P < 10−288) and provides evidence that TEADs are the predominant co-factors facilitating YAP1 association with chromatin in YAP1-amplified glioblastoma cancer cells." (PMID 26295846, 2015). "Although YAP1 is known primarily as the oncogene involved in the Hippo tumor suppressor pathway, the induction of YAP1 expression caused by an increase in the intracellular ROS concentration was described in glioblastoma cells." (PMID 28231263, 2017). "While Yap1‐5SA‐expressing cells were overall enriched in glioblastoma stem cell‐like signature across clusters, clusters 9 and 11 showed lower enrichment consistent with their partial, albeit aberrant differentiation." (PMID 37083045, 2023). "The degree of overexpression of YAP1 has also been shown to correlate with the degree of tumor progression in glioblastomas." (PMID 37626776, 2023). "Combined profiling and functional studies demonstrate that LDHA-directed ERK pathway activates YAP1/STAT3 transcriptional co-activators in glioblastoma cells to upregulate CCL2 and CCL7, which recruit macrophages into the tumor microenvironment." (PMID 37886538, 2023). "In particular, we observed deactivation of Yap-1 molecule in glioblastoma cells and the remodeling of VE-Cadherin junctional protein in endothelial cells." (PMID 35662260, 2022). "We first analyzed the correlation between ALKBH5 and YAP1 expression using the glioblastoma database of the Cancer Genome Atlas, (TCGA)." (PMID 33375621, 2020). "More importantly, we testify that IKBKE accelerates EMT of glioblastoma cells via IKBKE-dependent YAP1/TEAD2 activation." (PMID 28548934, 2017). "This novel YAP1 signature from YAP1-amplified glioblastoma cells should have predictive potential for the identification of YAP1-dependent tumors." (PMID 26295846, 2015). "This further argues that YAP1 association with chromatin is mainly mediated via TEAD TFs and specifically by TEAD1 in the tested glioblastoma setting." (PMID 26295846, 2015). "To evaluate the physiological relevance of these YAP1-activated target genes, we sought to predict YAP1 expression in tumor samples using expression data for 528 primary glioblastoma and 279 head and neck squamous cell tumor samples." (PMID 26295846, 2015). "Using a naïve Bayes classifier this allowed to predict YAP1 expression level with high accuracy (an area under the receiver operating characteristics curve (AUC) = 0.83 for glioblastoma samples and AUC = 0.78 for head and neck squamous tumor samples)." (PMID 26295846, 2015). "Verteporfin, an inhibitor of YAP1, has been shown to inhibit the interaction between YAP1 and TEAD, and a phase 1/2 study of visudyne (liposomal verteporfin) in patients with recurrent high-grade EGFR-mutated glioblastoma is recruiting [NCT04590664]." (PMID 38246995, 2024). "Finally, prolonged Yap1 activity in adult hippocampal NSCs disrupts physiological neurogenesis promoting aberrant cell differentiation and partial acquisition of a glioblastoma stem cell‐like signature." (PMID 37083045, 2023). "The highly aberrant transcriptional programs elicited by Yap1 gain‐of‐function may reflect processes that occur during glioblastoma formation." (PMID 37083045, 2023). "However, prolonged Yap1 activity disrupts the physiological molecular trajectory towards neurogenesis and instead induces a gene expression signature akin to glioblastoma stem cells and can lead to aberrant differentiation." (PMID 37083045, 2023).
glioblastoma (continued). "Consequently, dysregulated Yap1 activity led to repression of hippocampal neurogenesis, aberrant cell differentiation, and partial acquisition of a glioblastoma stem cell‐like signature." (PMID 37083045, 2023). "Zhang et al81 reported that IKBKE increased the expression of YAP1, promoted YAP1 translocation into the nucleus and decreased the expression of p‐YAP1 (Ser127), which was a degradative marker of YAP1, thereby promoting the progression of glioblastoma." (PMID 31733040, 2020). "These include PCa stages according to Gleason score, head and neck squamous cell carcinoma, and glioblastoma, suggesting that this co-regulation is imparted by increased YAP1 stability when NEK1 is overexpressed or activated by TLK1, and not through transcriptional co-expression." (PMID 33297404, 2020). "YAP1 is widely expressed in human brain tumors and promotes glioblastoma growth." (PMID 26943771, 2016). "Furthermore, since YAP-1 was regulated by actin-myosin contractility, utilizing Y-27632, which dysregulates actin dynamics and interrupts the cell-cell contact, significantly increased YAP-1 expression and dramatically decreased the survival fraction of glioblastoma after BNCT." (PMID 40896363, 2025). "Of note, YAP1 may be of interest as a therapeutic target because pharmacologic inhibition of YAP/TAZ dependent transcription has shown efficiency in pre-clinical studies of different cancer types including glioblastoma." (PMID 34967922, 2022). "HSPA7 was found to promote macrophage infiltration and SPP1 expression by upregulating YAP1 and LOX in glioblastoma stem cells (GSCs), both in vitro and in clinical GBM tumor samples." (PMID 39199429, 2024). "To confirm the role of LDHA in regulation of the YAP1/STAT3–CCL2/CCL7 signaling axis in vivo, we performed immunofluorescence for YAP1 and STAT3 in tumors and ELISA for CCL2 and CCL7 in plasma from control and LDHA-inhibited glioblastoma tumor-bearing mice." (PMID 38443336, 2024). "Mechanistically, LDHA-lactate-directed ERK pathway activates YAP1 and STAT3 transcriptional co-activators to upregulate CCL2 and CCL7 in glioblastoma cells, which promote macrophage infiltration into the TME." (PMID 38443336, 2024). "Together, these findings suggest that YAP1 and STAT3 transcriptional co-activators contribute to LDHA/lactate–ERK axis-dependent CCL2 and CCL7 expression in glioblastoma cells." (PMID 38443336, 2024). "Mechanistically, our study demonstrated that these two chemokines are regulated by LDHA/lactate-induced activation of YAP1 and STAT3 in glioblastoma cells." (PMID 38443336, 2024). "Here, we further identified that YAP1 activation promotes macrophage infiltration via direct transcriptional regulation of CCL2 and CCL7 in glioblastoma cells, consistent with the findings observed in liver cancer." (PMID 38443336, 2024). "In silico analysis of the downstream Hippo signalling members YAP1, TAZ and TEAD1 transcript levels in low‐grade glioblastoma (LGG) and GBM tumour tissues was performed using GEPIA." (PMID 39718433, 2024). "Together, these findings suggest that LDHA-directed ERK pathway regulates HOXA9, YAP1, and STAT3 transcription factors and/or signaling pathways in glioblastoma cells and GSCs." (PMID 38443336, 2024). "Another study found that m6A-regulated long non-coding RNA HSPA7 facilitated macrophage infiltration through the YAP1–LOX axis and enhanced the efficiency of anti-PD1 therapy in glioblastoma." (PMID 35936722, 2022). "YAP1 was upregulated in DLBC (lymphoid neoplasm diffuse large B-cell lymphoma), GBM (glioblastoma multiforme), PAAD (pancreatic adenocarcinoma), STAD (stomach adenocarcinoma) and THYM (thymoma)." (PMID 34257617, 2021). "One study in glioblastoma showed that TNFα stimulation decreased p-ERK expression, led to reduction of YAP1 expression." (PMID 31848326, 2019).
glioblastoma (continued). "These researches and our experimental data provide the theoretical basis that IKBKE promotes glioblastoma growth and EMT through IKBKE-dependent YAP1/TEAD2 activation." (PMID 28548934, 2017). "To gain insight into YAP1 genomic recruitment in a YAP1-relevant cancer context, we used SF268 glioblastoma cells, previously demonstrated to have elevated YAP1 activity due to a 13-fold genomic amplification of the YAP1 locus." (PMID 26295846, 2015). "Moreover, treatment with EMφ EVs upregulated the levels of P-ERK, YAP1, P-STAT3, CCL2, and CCL7 in glioblastoma cells." (PMID 38443336, 2024). "Moreover, bioinformatics analyses in TCGA glioblastoma dataset confirmed that LDHA, YAP1, STAT3, CCL2, and CCL7 positively correlated with each other and with macrophage signature in patient tumors." (PMID 38443336, 2024). "Involvement of the inactivated hippo pathway due to decreased expression of MST1/2 or LATS1/2 or even due to the overactivation of YAP1 and TAZ has been confirmed in various tumor types, such as colorectal and prostate cancer and even in astrocytomas and glioblastomas." (PMID 37626776, 2023). "It has been reported that YAP1 inhibition by Verteporfin does not enhance the antitumor efficacy of temozolomide in glioblastoma." (PMID 35356283, 2022). "FOXM1 expression in glioblastoma stem like cells has been shown to be elevated via FGFR signaling, wherein the expression of FGFR has been found to be elevated via α6-integrin and ZEB1/YAP1 transcription factor complex." (PMID 33680951, 2020). "Specific binding of YAP1 and H3K27ac to the LOX promoter was confirmed in glioblastoma cell models." (PMID 32708046, 2020). "Furthermore, SRC/AKT/YAP1 and YAP1/LOX signaling were shown to positively correlate with macrophage density and reduced overall survival in glioblastoma multiforme patients." (PMID 32708046, 2020). "The glioblastoma database of the Cancer Genome Atlas, (TCGA, n = 539) was used to analyze the correlations between α6-integrin expression and several potential target genes including ZEB1, YAP1, FGFR1, and FOXM1." (PMID 30909436, 2019). "Additionally, we respectively overexpress YAP1 and TEAD2 in glioblastoma cell lines transfected with IKBKE-shRNA." (PMID 28548934, 2017). "Accordingly, YAP1 mRNA and protein levels are increased in SF268 cells as compared to LN229 glioblastoma cells that do not harbor any genetic aberrations of YAP1/Hippo pathway components." (PMID 26295846, 2015). "Furthermore, immunofluorescent images showed a larger YAP-1 expression area within spheroid after Y-27632 treatment, confirming that the interrupting of the cell-cell force interaction indeed activated YAP-1 in glioblastoma spheroids." (PMID 40896363, 2025). "To further investigate whether LDHA-regulated lactate contributes to this process, we treated LDHA-depleted glioblastoma cells with lactate and found that this treatment rescued the impaired signaling of P-ERK, YAP1, P-STAT3, CCL2, and CCL7 in shLdha CT2A cells." (PMID 38443336, 2024). "We confirmed that HSPA7 promoted macrophage infiltration and SPP1 expression via upregulating the YAP1 and LOX expression of glioblastoma stem cells (GSCs) in vitro and in our clinical GBM tumor samples." (PMID 34354698, 2021). "Similarly, in head and neck squamous cell carcinoma, glioblastoma, and other cancers (data not shown), there was no significant upregulation of YAP1 mRNA expression; nonetheless, YAP1 protein level was elevated in high-grade metastatic tumors." (PMID 33297404, 2020). "Similarly, Zhang et al81 discovered that miR‐let‐7b/i could decrease the expression of IKBKE, while IKBKE also decreased the expression of miR‐let‐7b/i through inducing YAP1, thus forming a miR‐let‐7/IKBKE/YAP1 regulatory loop to regulate glioblastoma cell growth." (PMID 31733040, 2020). "The decreased P-ERK, YAP1, P-STAT3, CCL2, and CCL7 in LDHA-depleted glioblastoma cells was rescued by the treatment with EMφ EVs, but not LDHA-depleted EMφ EVs." (PMID 38443336, 2024).